S100B (S100 calcium binding protein B)
Diseases named in the same sentence as S100B in open-access papers (continued):
Sharing a sentence is not in itself a finding about the gene and the disease.
melanoma (continued). "If confirmed, the endogenous formation of S100BSNO in melanoma cells would have be taken under consideration in the on-going drug discovery process for melanoma treatment based on small molecule inhibitors directly targeting S100B." (PMID 27159591, 2016). "Moreover, following vaccination with modified autologous melanoma cells as postsurgical adjuvant therapy, the changes in postvaccination serum CEACAM1 correlate with overall survival and with the S100B melanoma marker." (PMID 26688824, 2015). "S100B and Melan-A proteins are present in melanocytes and most melanomas." (PMID 24811334, 2014). "In a recent paper, Kruijff and Hoekstra (2012) state that the protein S-100B is probably the best biomarker for melanoma, having potential to identify high-risk stage III melanoma patients who may benefit from adjuvant systematic treatment." (PMID 23509441, 2013). "Patients suffering from malignant melanomas might present “false” high S100B levels after traumatic brain injury which has to be considered when there seems to be a discrepancy between clinical findings and the serum level of S100B." (PMID 23509442, 2013). "Serum S100B protein concentration in stage II-IV melanoma is a reliable prognostic marker." (PMID 23166536, 2012). "There might have been amplification of the S-100B concentrations of intra-cranial origin due to the widespread malignant melanoma, especially from the tumor located within the dura where surgery might have induced S-100B release." (PMID 23227020, 2012). "Clinically, S-100B is also the most widely used biomarker in malignant melanoma patients." (PMID 23227020, 2012). "It is surprising that in FDG PET/CT negative patients, no patient showed elevated serum level of MIA or S100B or melanoma associated death during follow up." (PMID 21935432, 2011). "Serum S100B is a valuable prognostic marker for assessment of melanoma mortality." (PMID 21935432, 2011). "Dct expression correlates with the presence of S100B+ melanoma cells detected by IHC." (PMID 21980263, 2011). "The prognostic value of PET/CT in high risk melanoma patients compared to the tumor markers S100B and MIA has not been assessed." (PMID 21935432, 2011). "Also, S100B may serve as a reliable baseline marker for OS in melanoma patients undergoing anti-PD-1 therapy." (PMID 39766118, 2024). "However, it is important to keep in mind that mutations in the BRAF oncogene are not found in all melanoma patients, so we tested its combination with the conventional protein tumor biomarker S100B to identify high‐risk patients." (PMID 39387479, 2024). "Our approach could be broadly applicable to most melanoma cases, irrespective of S100B CN gain or loss because the CRISPR/Cas9 system can intrinsically suppress multiple copies of the same gene." (PMID 36899866, 2023). "Additionally, serum S100B levels tend to be elevated in central nervous system-related pathological conditions, neurodegenerative diseases, certain psychiatric disorders, and in cases of brain tumors and brain metastases, including melanoma brain metastases." (PMID 38202181, 2023). "Therefore, it is plausible that inhibition of IL6/ STAT3 pathway by elevated S100B in melanoma cells could be beneficial to early stage tumors as a way to prevent anti-proliferative effects of IL6 and to avoid immune-related destruction." (PMID 34411141, 2021).
melanoma (continued). "Thus, elevated S100B reduces IL6-STAT3 signaling via RSK signaling pathway in malignant melanoma." (PMID 34411141, 2021). "When secreted into the tumor milieu, S100B produced by melanoma cells could act in a paracrine manner on the nearby endothelial cells, resulting in activation of the S100B/RAGE axis, activation of NF-κB, and the recruitment of immune cells to the tumors, sustaining an inflammatory microenvironment." (PMID 33256110, 2020). "One reason could be the limited dynamic range of LDH values in the serum of cancer patients which encompasses approximately one order of magnitude whereas S100B in the serum of melanoma patients ranges from below 0.11 μg/L to levels above 10.0 μg/L, suggesting a significantly greater sensitivity." (PMID 32188047, 2020). "Nevertheless, two patients in our study demonstrated an immediate and parallel decrease of IL-6 and S100B serum levels after administration of checkpoint inhibitor treatment which might result from a direct suppressive effect of PD-1 blockade on melanoma cell cycle." (PMID 32188047, 2020). "Moreover, serum S100B level increases in patients with melanoma, independently of the cancer stage." (PMID 31330795, 2019). "However, in contrast to breast cancer, there is an overexpression of S100B in melanoma cells, which may explain the higher level of serum S100B in the brain metastases from malignant melanoma." (PMID 24179506, 2013). "In this case, melanoma (tumor) cells can be distinguished by SOX10, S100B, and CD63 protein abundance." (PMID 41333415, 2025). "Except for S100B, the serum concentration of TIMP-1 is perceived as another promising biomarker in melanoma 58,59." (PMID 40535809, 2025). "In univariable analysis, factors associated with an increased risk of MBM development were T-stage at primary tumor diagnosis, metastatic stage, plasma levels of S100B, plasma levels of LDH, and first-line treatment at advanced melanoma diagnosis." (PMID 40217072, 2025). "All the PDX tumors exhibited confirmatory markers of melanoma, such as SOX10, MELAN-A (MART1), HMB45, or S100B." (PMID 39312285, 2024). "Similar to preoperative levels, higher level of S100B in postoperative plasma sample (cut‐off value 0.1466 μg/L) was not predictive for patients’ DFI (p = 0.573), OS (p = 0.208), or melanoma recurrence (p = 0.438)." (PMID 39387479, 2024). "The results of the test were positive for MLANA, S100β, PNL2, TRP1, and TRP2, confirming that this was a malignant melanoma." (PMID 38891124, 2024). "A blood-based, seven-miRNA subset (MELmiR-7) detected melanoma with high sensitivity (93%) and specificity (≥82%), and it outperformed standard markers (LDH and S100B) for predicting OS." (PMID 39766118, 2024). "For a more accurate characterization of the cell lines, we used a combination of several melanoma indicators in addition to the two indicators, MLANA and S100β, that are routinely recommended for clinical use." (PMID 38891124, 2024). "For example, S100B is a known marker of melanoma, and some other members of the S100A family, like S100A2 and S100A6, are thought to have a role in the progression of melanoma from normal melanocytes to metastatic disease." (PMID 38892279, 2024). "Three lipids (CE(12:0), FFA(24:1), and TAG47:2-FA16:1) were identified as more effective predictors of melanoma metastasis than the well-known markers LDH and S100B." (PMID 38673837, 2024). "Similar to S100B, research indicates that MIA exhibits greater sensitivity, specificity, and accuracy in identifying melanoma metastasis compared to other tumor markers." (PMID 39766118, 2024). "At the chromatin level, we observed an event of epigenetic priming at the S100B promoter, such that the TSS at the upstream promoter showed enrichment for DHS in SK-MEL-5 melanoma cells." (PMID 36899866, 2023).
melanoma (continued). "The immunoassays were performed to detect the serum levels of S100B protein and the plasma levels of MIA protein in blood samples from melanoma patients at different stages of disease progression." (PMID 37373887, 2023). "In a meta-analysis, we previously found that both serum S100B and serum LDH are valuable prognostic markers in advanced melanoma patients." (PMID 37664072, 2023). "At the systemic level, the S100B protein, along with lactate dehydrogenase (LDH), is routinely investigated in melanoma management." (PMID 37373887, 2023). "We aimed to determine the anti-PD-1 treatment related prognostic performance of demographics, clinical and histological prognostic markers and baseline serum S100B and LDH levels in advanced melanoma." (PMID 37664072, 2023). "The ‘MELmiR-7’ panel characterizes overall survival of melanoma patients better than both serum LDH and S100B." (PMID 36835424, 2023). "Experimental data were obtained after performing the immunoassays for detecting the S100B and MIA expression levels in the peripheral blood collected from a study group of 176 melanoma patients." (PMID 37373887, 2023). "S100 subtypes: S100B, S100P, S100A4, S100A6, and S100A13 are often found in melanoma, with S100P being positive in all melanoma subtypes." (PMID 37504268, 2023). "We observed epigenetic priming in the melanoma cells, such that DHS enrichment was observed in SK-MEL-5 cells at the S100B TSS and upstream promoter, which spans 578 bp (chr21:46,604,961-46,605,537)." (PMID 36899866, 2023). "First, we identified tumor cells by inferred large-scale CNVs from single-cell expression profiles and newly identified PMEL, S100B, SERPINE2, TYR, and PRAME as marker genes for melanoma malignant cells." (PMID 35646893, 2022). "The combination of these two miRNAs showed a higher efficiency to diagnose melanoma patients than the known biomarkers Lactate dehydrogenase (LDH), MIA, or S100B alone or in combination." (PMID 36704194, 2022). "In another study, the levels of Melanoma inhibitory activity protein (MIA), S100B and tyrosinase-related protein 2 (TYRP2), known melanoma biomarkers, were evaluated in exosomes isolated from the sera of stage IV melanoma patients and healthy controls." (PMID 36704194, 2022). "Together, these studies show that elevated S100B suppresses IL6 and STAT3 transcriptional activity in malignant melanoma." (PMID 34411141, 2021). "Collectively, these data continue to support a mechanism in which elevated S100B found in malignant melanoma negatively regulates the IL6/STAT3 pathway and that functional IL6 can be restored when S100B expression is inhibited." (PMID 34411141, 2021). "Elevated levels of S100B(ββ) also dysregulate ERK/RSK signalling and increase cell survival in malignant melanoma." (PMID 33573254, 2021). "S100B and lactate dehydrogenase (LDH) served as serum tumor markers for monitoring malignant melanoma." (PMID 32188047, 2020). "When injected into mice, we showed that the RAGE overexpressing melanoma tumors expressed higher levels of S100B than WM115 control tumors, suggesting a positive correlation between RAGE, S100B, and melanoma malignancy." (PMID 33256110, 2020). "Melanoma-derived growth regulatory protein (MIA) and S100B protein were detected in exosomes from serum of CM patients and their quantification presented with diagnostic and prognostic potential towards stage IV of CM." (PMID 32331267, 2020). "Melanoma markers routinely used in clinical practice for staging, prognostics, treatment selection, and follow-up include lactate dehydrogenase (LDH), S100B protein, melanoma inhibitory activity (MIA) protein, and BRAFV600E mutation." (PMID 31086060, 2019). "Three melanoma cell lines (BAK, BUL, and STU) were established and immunostained for melanocyte-specific antigens MART1 and S100β." (PMID 31379943, 2019).
melanoma (continued). "Serum levels of several proteins, such as S100β, CRP, melanoma inhibitory activity (MIA) protein and LDH have been suggested as early biomarker candidates, but they do not seem to improve patient sub-classification into specific prognostic groups." (PMID 31803364, 2019). "Firstly, the levels of established melanoma biomarkers, namely MIA, S100B, and tyrosinase-related protein 2 (TYRP2), were compared between exosomes isolated from the sera and total serum samples of stage IV melanoma patients and healthy controls." (PMID 31086060, 2019). "We found that SA-4 cells also express several genes typical of melanomas, such as MITF, MLANA, S100B, and TYR, which are otherwise poorly expressed in our panel of liposarcoma cell lines." (PMID 29570692, 2018). "Exo isolated from the sera of melanoma patients express higher amounts of CAV-1, S100B, and MIA (melanoma inhibitory activity) than measured in healthy controls." (PMID 29755693, 2018). "The half-life of S100B has been shown to be in the range of 60 to 120 min in patients with TBI and 90 min in patients suffering from malignant melanoma." (PMID 27957604, 2017). "Despite the differences in tumour size at day 14, the expression of S100B in blood samples from HIF-1α KO, indicative of the number of circulating melanoma cells was found elevated comparable to WT mice." (PMID 29150606, 2017). "S100B, melanoma inhibitory activity (MIA) and lactate dehydrogenase (LDH) are the most widely used biomarkers for the metastatic developmental stage of melanoma, but they have very low sensitivity." (PMID 29238879, 2017). "We have for instance seen extreme increases of S100B in serum in a patient with mild TBI and malignant melanoma." (PMID 27957604, 2017). "To further investigate the ability of our generated antibody to detect metastatic melanoma cells we performed immunostainings with MHA-3 and S100b." (PMID 27853253, 2016). "Stainings with H&E and antibodies against the highly characterized melanoma markers S100B, HMB-45A and Melan-A revealed the highly cellular growth pattern of melanoma, and resemblance to the tumor biopsies from patients was observed." (PMID 25228592, 2014). "It therefore appears inappropriate to consider differential levels of S-100B as indicative of the evolution of CSH, as suggested by the paper's title, since they can be more indicative of a melanoma and its metastasis." (PMID 23509441, 2013). "Several studies showed the prognostic value of S100B and LDH in predicting successful therapeutic treatments for malignant melanoma patients." (PMID 22291846, 2012). "Currently, the two most widely used melanoma biomarkers are lactate dehydrogenase (LDH) and the calcium binding protein S100B." (PMID 22291846, 2012). "A subsequent study of 373 melanoma patients evaluating the combination of S100B, MIA, LDH, and albumin as biomarkers reported that S100B had the greatest sensitivity for detecting new metastases compared to MIA, LDH, or albumin." (PMID 22220281, 2011). "Further study is needed to assess the utility of S100B and MIA as well as the frequency with which these tests should be performed in clinically disease free melanoma patients." (PMID 24281112, 2010). "Although MIA is less commonly used than S100B or LDH in clinical practice, it provides greater specificity for melanoma and may have added value when combined with other biomarkers." (PMID 40981345, 2025). "Unlike S100B, calprotectin is not synthesized by melanoma cells themselves but is predominantly produced by neutrophils, monocytes, and keratinocytes within the tumor microenvironment, particularly under conditions of cellular stress or inflammation." (PMID 40869349, 2025). "Furthermore, we have assessed the expression of the PMEL and Melan-A markers and the S100B and TIMP-1 protein levels in representative blood samples from melanoma patients and healthy controls." (PMID 40535809, 2025).
melanoma (continued). "Unlike NfL, serum S100B levels (also a melanoma biomarker) only differentiated definite ICI-encephalitis from cancer-matched controls after excluding patients with melanoma." (PMID 40181971, 2025). "Serum S100β measurement is not routinely recommended for surveillance of asymptomatic patients with melanoma in the United States." (PMID 40941017, 2025). "This goal was completed using a comparison of CMC numbers, including their pre- and post-treatment status, evaluation of PMEL and Melan-A marker expression, and assessment of serum levels of S100B and TIMP-1 proteins in representative blood samples from melanoma patients and healthy controls." (PMID 40535809, 2025). "In several studies from that period, S100B was found to be present at elevated levels in melanoma tumor biopsies but not in normal skin samples and non-melanoma tumors." (PMID 38892279, 2024). "As a result, repeated serum S100B analyses were available from ICI-treated S100B negative patients with melanoma with and without CNS irAE." (PMID 38171113, 2024). "Higher level of S100B in preoperative plasma sample compared to lower level (cut‐off value 0.0714 μg/L) was not predictive for patients’ DFI (p = 0.261), OS (p = 0.328), or melanoma recurrence (p = 0.332)." (PMID 39387479, 2024). "As for S100B, it is a valuable serum biomarker in the follow‐up of stage III and IV melanoma patients, particularly in early detection of progressive disease as well as in the prediction response to BRAF inhibitors and anti‐programmed cell death protein 1 (PD‐1) therapy." (PMID 38775220, 2024). "Selective combination of S100b-specific single-guide RNAs and the dCas9-KRAB fusion significantly suppressed expression of S100b in murine B16 melanoma cells without noticeable off-target effects." (PMID 36899866, 2023). "We investigated the S100B and MIA levels in peripheral blood from 176 melanoma patients." (PMID 37373887, 2023). "The study showed that melanoma patients had significantly higher S100B and MIA exosomal concentrations than the negative controls analyzed." (PMID 36835424, 2023). "There are some applications in which several biosensors are for the detection of several diseases Lactate dehydrogenase (LDH) is the earliest prognostic biomarker of melanoma as well as serum s100B level, BRAF V600, Tyrosinase mRNA are the biomarkers used for the detection of melanoma." (PMID 37803407, 2023). "Importantly, the prognostic value of serum S100B and LDH levels seemed to be very pronounced in patients diagnosed with a pT4b primary melanoma." (PMID 37664072, 2023). "Therefore, we analyzed in CM the interrelationship between the S100B and MIA blood levels and also between the tissue expression of the S100 protein and the other two specific melanoma markers, MelanA and gp100 (HMB45)." (PMID 37373887, 2023). "Nevertheless, the questions remain open about the validity of measuring serum S100B levels for detecting melanoma relapse, and there is still no consensus on the necessity for peripheral blood sampling in the follow-up of melanoma patients." (PMID 38202181, 2023). "Additionally, it exhibited superior performance in detecting melanoma recurrences compared to serum measurements of LDH and S100B." (PMID 38201222, 2023).